PRIMPOL (primase and DNA directed polymerase)
Description:
DNA primase and DNA polymerase required to tolerate replication-stalling lesions by bypassing them. Required to facilitate mitochondrial and nuclear replication fork progression by initiating de novo DNA synthesis using dNTPs and acting as an error-prone DNA polymerase able to bypass certain DNA lesions. Shows a high capacity to tolerate DNA damage lesions such as 8oxoG and abasic sites in DNA. Provides different translesion synthesis alternatives when DNA replication is stalled: able to synthesize DNA primers downstream of lesions, such as ultraviolet (UV) lesions, R-loops and G-quadruplexes, to allow DNA replication to continue. Can also realign primers ahead of 'unreadable lesions' such as abasic sites and 6-4 photoproduct (6-4 pyrimidine-pyrimidinone), thereby skipping the lesion. Repriming avoids fork degradation while leading to accumulation of internal ssDNA gaps behind the forks. Also able to incorporate nucleotides opposite DNA lesions such as 8oxoG, like a regular translesion synthesis DNA polymerase. Also required for reinitiating stalled forks after UV damage during nuclear DNA replication. Required for mitochondrial DNA (mtDNA) synthesis and replication, by reinitiating synthesis after UV damage or in the presence of chain-terminating nucleotides. Prevents APOBEC family-mediated DNA mutagenesis by repriming downstream of abasic site to prohibit error-prone translesion synthesis (By similarity). Has non-overlapping function with POLH. In addition to its role in DNA damage response, also required to maintain efficient nuclear and mitochondrial DNA replication in unperturbed cells.
Synonyms: CCDC111; FLJ33167; MYP22; Primpol1
Tractability: Small molecule: a structure with a bound ligand is known. PROTAC: ubiquitination databases record sites on it.
Gene: Protein-coding gene on chromosome 4 (184,648,461 to 184,694,963, forward strand). Ensembl gene ENSG00000164306.
Subcellular location: Nucleus; Mitochondrion matrix; Chromosome
Subcellular location (Human Protein Atlas): Cytosol; Nucleoplasm
Gene Ontology:
Molecular function: chromatin binding; DNA polymerase activity; DNA-directed DNA polymerase activity; DNA-directed RNA polymerase activity; manganese ion binding; protein binding; zinc ion binding
Biological process: error-prone translesion synthesis; mitochondrial DNA replication; R-loop processing; replication fork processing; response to UV; translesion synthesis; mitochondrial DNA repair; DNA replication, synthesis of primer; DNA-templated DNA replication
Cellular component: chromosome; mitochondrial matrix; mitochondrion; nucleoplasm; nucleus; replication fork
Genetic constraint (gnomAD): Loss-of-function variants: 22 observed, 27.36 expected, observed/expected ratio (o/e) 0.8, 90% interval 0.57 to 1.15. The upper end of that interval is the gene's LOEUF score, 1.15, which puts it in group 5 of 6, group 1 being the genes least tolerant of losing a copy. Missense variants: 363 observed, 395.69 expected, observed/expected ratio (o/e) 0.92, 90% interval 0.84 to 1. Synonymous variants: 133 observed, 141.38 expected, observed/expected ratio (o/e) 0.94, 90% interval 0.82 to 1.09.
Homologues: Orthologues: macaque PRIMPOL (96% identical), dog PRIMPOL (80% identical), guinea pig PRIMPOL (78% identical), chimpanzee PRIMPOL (76% identical), pig PRIMPOL (74% identical), rat Primpol (73% identical), mouse Primpol (72% identical), zebrafish primpol (46% identical), tropical clawed frog primpol (23% identical).
Diseases named in the same sentence as PRIMPOL in open-access papers:
PRIMPOL is named in the same sentence as 22 diseases in open-access papers, as found by Europe PMC text mining. Sharing a sentence is not in itself a finding about the gene and the disease. The quoted sentences say what the papers report.
myopia (4 papers, 2014 to 2020). "For example, a mutation of human PrimPol has been identified in individuals with high myopia and is associated with defective DNA replication, significantly reducing its polymerase activity." (PMID 26109351, 2015). "Here, we report that the Y89D variant of PrimPol, previously found to be associated with high myopia, is a low processivity variant of PrimPol." (PMID 25262353, 2014). "While we have characterized a single mutation in this study, other mutations of PrimPol in other disease contexts such as myopia or adenocarcinomas have been identified that could be further explored." (PMID 32518272, 2020). "However, exome sequencing of the genomes of candidate patients has recently implicated the PrimPol gene as a possible susceptibility gene associated with high myopia." (PMID 25262353, 2014). "The PRIMPOL variant (p.Y89D) segregated with the disease and was absent in 270 Chinese controls, which implicated it in high myopia." (PMID 32375772, 2020).
breast carcinoma (3 papers, 2016 to 2023). "Kaplan–Meier plotter survival analysis also showed that PRIMPOL expression was significantly associated with the prognosis of breast cancer and lung cancer." (PMID 37391787, 2023). "The highest number of PRIMPOL deficient tumours was observed in breast cancer patients diagnosed with invasive breast cancer (1.7%; 14 out of 817), consisting of invasive lobular carcinoma or invasive ductal carcinoma, or a mixed group." (PMID 26926109, 2016). "The study reported a high number of PRIMPOL-deficient tumors in breast cancer patients diagnosed with invasive lobular and ductal carcinoma, and the PRIMPOL−/− tumors were found to exhibit a mutation load that was nearly twice as high as in PRIMPOL-proficient tumors." (PMID 28754021, 2017).
ovarian carcinoma (3 papers, 2020 to 2024). A malignant neoplasm originating from the surface ovarian epithelium. "It has been shown that USP36 is crucial in ovarian cancer development due to its direct deubiquitylation for PrimPol, of which overexpression correlates with poor prognosis." (PMID 38517383, 2024). "A positive correlation between USP36 and PrimPol protein levels (P = 0.0286, Pearson r = 0.7205) was observed in ovarian cancer cell lines." (PMID 33237263, 2020). "Recent findings have reported that the upregulation and increased chromatin recruitment of the PrimPol protein in ovarian cancer cells." (PMID 33237263, 2020). "To test our hypothesis, we examined the correlation between the expression of USP36 and PrimPol proteins in human ovarian cancer cells and specimens." (PMID 33237263, 2020). "In ovarian cancer tissues, USP36 overexpression is observed to positively correlate with the level of PrimPol expression and poor prognosis, indicating that the USP36-PrimPol axis may play an important regulatory mechanism in the cancer pathogenesis and treatment." (PMID 33237263, 2020).
endometrial cancer (2 papers, 2021 to 2023). Primary or metastatic malignant neoplasm involving the endometrium (mucous membrane that lines the endometrial cavity). "The incidence of PRIMPOL "mutation" is highest in endometrial cancer." (PMID 37391787, 2023).
Fanconi Anaemia (2 papers, 2024). "ICL traversal also depends on ATR and the Fanconi anemia pathway and involves, among other proteins, FANCM, FANCD2 and PRIMPOL." (PMID 39766854, 2024). "Surprisingly, guides targeting the fork reversal factors (SMARCAL1, HLTF, ZRANB3, SHPRH) or components of the Fanconi Anaemia pathway were neither enriched nor depleted, despite previous studies suggesting a genetic interaction between some of these factors and PRIMPOL in transformed cell lines." (PMID 37971291, 2024).
glioblastoma (2 papers, 2021 to 2023). The most malignant astrocytic tumor (WHO grade IV). "Additionally, PrimPol alterations have been observed in cancers, with overexpression of PrimPol reported in glioblastoma and a point mutation identified in lung cancer." (PMID 33744934, 2021). "PRIMPOL was upregulated in glioblastoma multiforme and kidney renal clear cell carcinoma." (PMID 37391787, 2023).
invasive breast carcinoma (2 papers, 2016 to 2019). A carcinoma that infiltrates the breast parenchyma. "Consistent with the anti-mutagenic activity of PrimPol during SHM, the level of PRIMPOL expression correlated negatively with the mutation load in invasive breast cancers." (PMID 26926109, 2016). "The notion that PRIMPOL acts as conservator of the genome is supported by the anti-mutagenic activity of PRIMPOL on AID family APOBEC induced mutagenesis in invasive breast cancer." (PMID 30915081, 2019). "However, the difference between murine SHM and APOBEC3B mutagenesis in human invasive breast cancer is that PRIMPOL affects C/G transversions and transition in invasive breast cancer, whereas only C>G transversion are affected by PrimPol in our SHM readout." (PMID 26926109, 2016).
colorectal cancer (1 paper, 2024). A primary or metastatic malignant neoplasm that affects the colon or rectum. "To this end, we overexpressed PRIMPOL in DLD1 colorectal cancer and 8988T pancreatic cancer cell lines." (PMID 39530221, 2024).
melanoma (1 paper, 2025). A malignant, usually aggressive tumor composed of atypical, neoplastic melanocytes. "Conversely, downregulation of POLH and PRIMPOL, which are essential for DNA damage tolerance, particularly against UV-induced lesions, predisposes to melanoma." (PMID 41465101, 2025).
cancer (19 papers, 2017 to 2026). A tumor composed of atypical neoplastic, often pleomorphic cells that invade other tissues. "Recent studies indicated that primase polymerase (PRIMPOL) is strongly associated with the development of human cancers." (PMID 37391787, 2023). "The aberrant expression of PRIMPOL was linked to various cancer-associated pathways, including DNA damage response, DNA repair, and angiogenesis, according to single-cell sequencing and function enrichment." (PMID 37391787, 2023). "We discovered that the levels of PRIMPOL were positively interrelated with the penetration of cancer-associated fibroblasts (CAF) in a considerable number of tumors, including ESCA, HNSC, LGG, PAAD, STAD and TGCT." (PMID 37391787, 2023). "Unlike most DNA polymerases, PRIMPOL has dual primase and polymerase activities, and PRIMPOL defects have been linked to genome instability and cancer." (PMID 38069223, 2023). "Of note, loss of PRIMPOL in BRCA1-deficient cancer cells significantly affects cell growth and viability, even in the absence of exogenous damage, underscoring the relevance of the PRIMPOL pathway for BRCA1-deficient cell survival." (PMID 31676232, 2020). "A range of PrimPol mutations have been found in cancer cells and other conditions suggesting possible connections to human disease, including mitopathies, although these pathological associations remain to be established." (PMID 28408491, 2017). "PRIMPOL (also known as CCDC111) is an enzyme with both primase and polymerase activity that is responsible for the efficient progression of replication forks, and replication stress is strongly associated with the development of cancer." (PMID 37391787, 2023). "Another scenario, in which cancer cells could show high PrimPol activity, is in the presence of inactivating mutations in genes that negatively regulate PrimPol." (PMID 35204749, 2022). "Nevertheless, the established roles of PrimPol in DNA damage tolerance and mitochondrial DNA replication suggest that PrimPol mutations could lead to some inherited diseases including cancer predisposition and mitochondriopathies." (PMID 28754021, 2017). "Given the important effects of abnormal genomic changes in the malignant tumors, we investigated the genetic alterations of PRIMPOL in various human tumors." (PMID 37391787, 2023). "Accordingly, a recent study found that BRCA1/2-defective cancer cells rely much more on TLS for repair of PRIMPOL-dependent ssDNA gaps." (PMID 36749784, 2023). "In the last part, we used the enrichment analysis to evaluate the functional roles of PRIMPOL in cancers." (PMID 37391787, 2023). "Overall, these findings collectively suggested the potential effects of PRIMPOL in cancer pathogenesis." (PMID 37391787, 2023). "This pan-cancer analysis offers a thorough review of the functional roles of PRIMPOL in human cancers, suggesting PRIMPOL as a potentially important biomarker for the progression and immunotherapy of various cancers." (PMID 37391787, 2023). "Considering the versatility and relevance of PrimPol in DNA replication, new studies that shed light on the biochemistry and in vivo activity of this enzyme will have an impact on cancer therapy and other applications." (PMID 35204749, 2022). "Collectively, our results establish a new paradigm for the PRIMPOL protein in replication fork protection and revisit current models for how BRCA1-deficient cancer cells cope with cisplatin-induced lesions." (PMID 31676232, 2020). "We therefore generated these cancer-related PrimPol RBD mutants (F522V and I554T) in RBM-B-KO and RBM-A-KO backgrounds, respectively and analysed their binding to RPA70N using GFC." (PMID 28534480, 2017). "PRIMPOL is also attracting attention as a new target for cancer therapy." (PMID 41372167, 2025). "These comprehensive results could reveal the latent molecular mechanisms and biological functions of PRIMPOL in the occurrence, progression and clinical prognosis for patients with malignant tumors." (PMID 37391787, 2023).
cancer (continued). "Taken together, these results demonstrated that changes in PRIMPOL promoter methylation may be a key factor in the abnormal expression of PRIMPOL in cancer." (PMID 37391787, 2023). "Notably, REV1- Polζ was recently identified to have a protective and mutagenic role in BRCA1/2 mutant cancer cells by filling in PRIMPOL-dependent ssDNA gaps that arise in these cells upon replication fork stalling at SMUG1-mediated DNA lesions." (PMID 36075897, 2022). "Finally, we explore the available data on human PrimPol expression in different tissues in physiological conditions and its role in cancer." (PMID 35204749, 2022). "Altogether, these data suggest that the perturbation of PrimPol could have an effect on cancer development." (PMID 35204749, 2022). "The importance of PrimPol is underscored by the finding that PrimPol-mediated adaptive responses might decrease the efficiency of anti-cancer genotoxic drugs." (PMID 33237263, 2020). "Moreover, it is important to note that overexpression of PrimPol is correlated with prolonged survival of a subset of cancer cells, most likely by promoting the replication progression." (PMID 33237263, 2020). "Therefore, the study of the PrimPol and its regulatory network would not only reveal how PrimPol coordinates the dynamic reactions in DNA replication, but also provide novel targets for therapeutic intervention in cancers." (PMID 33237263, 2020). "Our study reveals a novel mechanism governing PrimPol protein stability by USP36 in human cancers." (PMID 33237263, 2020). "Further studies have shown that loss of PRIMPOL leads to increased cellular sensitivity to DNA cross-linking agents such as mitomycin C, suggesting that repriming of PRIMPOL may represent a novel target for improving the sensitivity of cancer cells to DNA-damaging chemotherapies." (PMID 36281462, 2022). "PRIMPOL expression was positively correlated with the levels of C4orf27, NPIPA1 (NPIP), RP4 (RHO) and SUGP2 (SFRS14) in pan-cancer." (PMID 37391787, 2023). "We provided clear evidence that cancer cells lacking BRCA proteins adapt to genotoxic stress by promoting PRIMPOL-dependent replication fork repriming at the expense of replication fork reversal, thereby avoiding toxic nascent strand degradation." (PMID 31676232, 2020).
tumor (5 papers, 2016 to 2025). "Consistent with the anti-mutagenic activity of PrimPol during SHM, the mutation load, including TpC mutations, was significantly increased in the PRIMPOL deficient tumour subset." (PMID 26926109, 2016). "Indeed, as expected and observed the overall mutation load nearly doubled in PRIMPOL deficient tumours (P-value<10−4, Mann-Whitney test)." (PMID 26926109, 2016). "If PRIMPOL exerts a critical anti-mutagenic activity, the overall frequency of point mutations, as determined by exome sequencing, is expected to increase in PRIMPOL deficient tumours as compared to the majority of PRIMPOL proficient tumours." (PMID 26926109, 2016). "Furthermore, point mutations were significantly increased at G/C and A/T base pairs and deletions in PRIMPOL deficient tumours." (PMID 26926109, 2016). "Taken together, these findings suggested the important regulatory roles of PRIMPOL in the tumor biological pathways." (PMID 37391787, 2023). "Accordingly, several algorithms, such as TIMER, EPIC and QUANTISEQ, were used to investigate the functional roles of PRIMPOL on the tumor-infiltrating immune cells." (PMID 37391787, 2023). "The levels of PRIMPOL possessed a positive interrelation with the tumor penetration of B cells in LUSC." (PMID 37391787, 2023). "The levels of PRIMPOL were identified to be positively related with the tumor infiltration of neutrophil cells in COAD and KIRC." (PMID 37391787, 2023). "The results showed that PRIMPOL was significantly involved in several tumor-related signaling pathways in multiple tumors such as CML and GBM." (PMID 37391787, 2023). "Understanding how cells adapt to genotoxic agents and how PrimPol mediates responses in replication fork restart has become increasingly important to optimize tumor therapy." (PMID 33237263, 2020). "The effect of PRIMPOL on mutations at TpC dinucleotides was strongest for C transversions (TpC>G, TpC>A), which is in line with anti-mutagenic activity of PRIMPOL in response to AP-sites generated by APOBEC3B in these tumours." (PMID 26926109, 2016). "Moreover, the levels of PRIMPOL displayed the positively correlation with the tumor infiltration of CD8 + T cells in STAD." (PMID 37391787, 2023). "Besides, in PRAD and STAD, PRIMPOL expression levels were positively correlated with the tumor infiltration of myeloid dendritic cells." (PMID 37391787, 2023). "Besides, in TGCT, the levels of PRIMPOL were positively interrelated with the tumor infiltration of Tregs." (PMID 37391787, 2023). "Patients with higher tumor mRNA levels of both ATR and PrimPol had a lower OS rate than those with KRAS-mutant tumors with lower mRNA levels of both ATR and PrimPol among patients with KRAS-mutant tumors in the LUAD cohort." (PMID 37591859, 2023). "It is known that the lack of PrimPol in mice results in a slight shortening of lifespan, increased incidence of late-onset tumor development, higher sensibility to UV-light injury, and impaired mitochondrial function (unpublished data)." (PMID 40725194, 2025). "However, there was no clear correlation was discovered between the levels of PRIMPOL and tumor infiltration of NK cells." (PMID 37391787, 2023).
genetic diseases (1 paper, 2021). "Since PrimPol is involved in an important mechanism that maintains replication restart in human cells, defects in this pathway are likely to have a role in genetic diseases." (PMID 33744934, 2021).
PRIMPOL also shares sentences with these, for which no sentence is quoted: lung carcinoma (2 papers); adenocarcinoma (1); aortic valve stenosis (1); ductal carcinoma (1); invasive ductal carcinoma (1); invasive lobular carcinoma (1); myoclonic-atonic epilepsy (1); pancreatic cancer (1); Thyroid Carcinoma (1); uterine corpus endometrial carcinoma (1).